TNF (tumor necrosis factor)
Diseases named in the same sentence as TNF in open-access papers (continued):
Sharing a sentence is not in itself a finding about the gene and the disease.
infection (continued). "TNF-α was significantly expressed in MDR-PA-infected RPE cells at 6 h (13.03-fold vs. 4.41-fold; p = 0.02) and 12 h (7.15-fold vs., 1.55-fold; p = 0.02) post-infection, while activation of IFN- γ was observed up to 12 h (>3-fold; p = 0.01)." (PMID 32423093, 2020). "Here, serum IL-6 and TNF levels in mice were not affected, however IL-10 was attenuated at 14 d post-infection." (PMID 32482929, 2020). "This fits the clinical picture in which increased values of IL-1β are detected together with TNFα in chronic low-grade peri-implant inflammation without any sign of infection." (PMID 33343230, 2020). "On admission to the ICU, patients who developed an infection during their hospital stay had lower TNF-α production in response to LPS compared to non-infected patients (86 vs 192 pg/mL, p = 0.030)." (PMID 33237337, 2020). "Furthermore, the anti-inflammatory effects of I3C appeared to be systemic as serum cytokines and chemokines markers (IL17, TNF-α, IL12 (p40, p70) and G-CSF) induced by Cr infection were all significantly attenuated in infected animals fed I3C diet." (PMID 33076301, 2020). "TNF-α is a pro-inflammatory cytokine that was recently determined to be an important host factor involved in neurological disorders and central nervous system inflammation during ZIKV human infection." (PMID 31947958, 2020). "However, infection was accompanied by the release of significantly enhanced levels of proinflammatory cytokines, including IFN-α2a, TNF-α, IL-6, and GM-CSF (P < 0.001 for each at MOI 1 compared with mock-infected controls)." (PMID 32088771, 2020). "Putting it all together it is clear that severe COVID 19 disease is associated with significantly increased leukocytes, neutrophils, infection biomarkers [such as CRP, PCT and ferritin] and cytokine levels [IL-2R, IL-6, IL-8, IL-10 and tumor necrosis factor (TNF)-α] and decreased lymphocyte counts." (PMID 33859967, 2020). "Unlike ADSCs, there was no increase in PGE2 release by THP-1 macrophages upon infection or treatment with IFNγ or TNFα." (PMID 32546788, 2020). "During MEF cell infection, complementation with chimera SseK1 and SseK3, but not SseK2, or respected DxD mutants, inhibited TNF-induced cell death." (PMID 32766249, 2020). "In the absence of infection, senescent cells show increased, low-grade, basal systemic inflammation (characterized by higher levels of IL-1β, IL-6, and tumor necrosis factor-α), which is known as inflammaging." (PMID 30940096, 2019). "Depletion of macrophages did not significantly affect mRNA levels of IL-10, TNF-α, or IL-23p19 during infection." (PMID 31455692, 2019). "They observed that liver TNF-α levels significantly increased in two different mouse strains (C3H/HePas and Balb/c) but not in C3H/HeJ mice at the third day of infection." (PMID 31687410, 2019). "Because we observed that intermediate monocytes express more TLR2 and TLR4 than classical and non-classical monocytes after infection with leishmania, we analyzed the frequency of cells expressing TNF and IL-10 on monocyte subsets expressing TLR2 and TLR4." (PMID 31119102, 2019). "This impairment might be related to significantly reduced expression in the bone marrow of IFN-γ, TNF-α and IFN-β in mice infected with Beijing-1585 and EAI-1627, which could be detected from the third day post infection onwards." (PMID 31882653, 2019). "This is contrasting with the effect of exogenous TNF-α, which has no protective role in established infection and its continuous administration leads to impaired anti-leishmanial activity." (PMID 31024534, 2019). "Compared to mock infection, RSV infection via both inoculation methods resulted in increased BAL concentrations of CCL2 (MCP-1), CCL5 (RANTES), CXCL1, CXCL10 (IP10), IFN-α, IFN-γ, and TNF." (PMID 31163619, 2019). "It is induced by TNFα and MDP and protects against infection with Listeria monocytogenes." (PMID 31229436, 2019).
infection (continued). "The differences in incidence rates of specific infections were not significant, except acute infectious diarrhea which also was less frequent in patients treated with TNF inhibitors (RR 0.17, 95% CI 0.03–0.85)." (PMID 31172410, 2019). "The distribution of the polymorphisms of CRP, TNF, and IL10 genes showed no significant changes irrespective of a previous infection or not with Chlamydia." (PMID 30804931, 2019). "Further, studies have also shown that infection of Syrian hamster results in immune responses that correspond to those observed in infected humans, with marked increases in IFN-γ, IL-2, TNF-α in the spleen, kidney, and heart, but reduced levels of these seen in the liver." (PMID 31632404, 2019). "Our previous studies demonstrated that LPS infection could activate the MAPK signaling pathway, and induce IL-6 and TNF-α overproduction." (PMID 30909903, 2019). "Induction of IL-6 was observed in SBCMV infected cell supernatants at 24 h after infection, but the induction of TNF-α was absent." (PMID 30909422, 2019). "Mice administered binge alcohol 0.5 or 3 h prior to infection did not exhibit a significant difference in GM-CSF, TNF-α, IL-12/p40 or IL-10 concentrations in lung tissue homogenates." (PMID 31821337, 2019). "However, when we evaluated infection-induced effects 2 weeks post-challenge, splenic CD8+ T cells from C57BL/6 and SV/129 mice showed a greater potential of TNF-α secretion, when compared to BALB/c animals (at least p ≤ 0.05 comparing normalized values)." (PMID 30881923, 2019). "The clinical signs, together with the pattern of increased TNF-α, IL-6, IL-12, IL-10 and IL-17 mRNA level observed in BVDV2-infected goat PBMCs in this study, suggested that BVDV-2 induced an acute inflammatory response in the early stage of infection." (PMID 31226933, 2019). "In any case, infected macrophages recruit additional circulating monocytes/macrophages and neutrophils to the site of infection via expression of chemokines (CCL2; CXCL10; and TNF); and the newly recruited cells in turn phagocytose the bacteria released by lysis of the infected AM." (PMID 31497538, 2019). "However, there was a trend of reduced TNF production at least by CD4+ and DN DC subsets upon infection with the PSM-secreting S. aureus USA300 WT strain." (PMID 31134074, 2019). "While the effects of TNF-α at the early defenses were insufficient to eliminate the infection with H99-α during the innate-phase, additional benefits of TNF-α production were observed during the adaptive phase of infection." (PMID 31404168, 2019). "On the other hand, an effect of TNF-α alone over the hRSV-infection has not been demonstrated with knockout mice." (PMID 30936869, 2019). "However, the infection of murine bone marrow-derived DCs with DCL-derived L. mexicana amastigotes not only promoted higher expression of IL-10 but also of IL-12 and TNF-α." (PMID 31847221, 2019). "Although GM-CSF, IL6 and IL12p35 were significantly up regulated after 12 h of infection, they were not up regulated after 24 h of infection, and additionally, TNF-α was not significantly expressed in IPAMs." (PMID 30918280, 2019). "In addition, the levels of pro-inflammatory cytokines (IL-2, IL-6, IL-12, TNF-α, IFN-α, IFN-γ) were higher in il10−/− mice than in wild-type mice at 1, 3, and 6 h post infection." (PMID 31551984, 2019). "Ex vivo analyses of monocytes demonstrated upregulation of interleukin-1 beta (IL-1β) and tumor necrosis factor alpha (TNF-α) mRNA and increased nitric oxide production during T. parva lethal infection compared to nonlethal infection at 10 dpi." (PMID 31570561, 2019). "A CD8+ T cell response with high levels of TNF-α and IFN-γ in a cytokine storm context has a major role in the pathology induced by this infection, as it has been described in C57BL/6 mice at 5 days post-infection." (PMID 31130923, 2019). "Intriguingly, we found that minocycline treatment did not block the increase in brain TNF-α expression induced by infection." (PMID 31488835, 2019).
infection (continued). "Studies also seem to suggest decreased stimulated production of tumor necrosis factor-alpha (TNF) when controlling for infection, without any suggestion of increased spontaneous release of TNF." (PMID 31717370, 2019). "Our previous study described that co-infected Ss infection with active or latent TB has significantly reduced Type 1 (IFN-γ, TNF-α, and IL-2), Type 17 (IL-17A and IL-17F) and increased regulatory as well as Type 2 (IL-4, IL-5, and IL-13) cytokines when compared to TB infection alone." (PMID 30897083, 2019). "It remains unclear why osteoclast activity is up-regulated during infection, but in this case, CGRP release from nociceptors becomes beneficial by suppressing two pathways: TNF-α release from myeloid cells and overactivation of osteoclasts." (PMID 31336748, 2019). "Further, the frequencies of CD8+T cells responding to challenge infection with a polyfunctional, cytolytic activation (Perforin+CD107+: 24–26.5%, Perforin+TNF-α+: 4.0–5.8%; CD95+CD95L+: 3.6–6.6%) were significantly increased in vaccinated/infected (vs. non-vaccinated/infected) mice (all, *p < 0.05)." (PMID 31293599, 2019). "This study demonstrated that infection with Mtb activates an antigen-specific, polyfunctional Th-1 response as the magnitude of PPD-specific IFN-γ+ IL-2+ TNF-α+ polyfunctional CD4+T-cells was greatest in the LTBI group (P = 0.0002) in comparison with the HC group." (PMID 31105706, 2019). "Interestingly, at early infection a significant proportion of IFN-γ and TNF-α producing cells predominantly from CD4+CD25− and CD4+FoxP3− T cell were observed." (PMID 31031744, 2019). "Indeed, HRV-infection of BE co-cultured with asthmatic BSM increased the production of pro-inflammatory mediators (IL-1A, IL-6, TNF-alpha) at the transcriptional level compared to that co-cultured with control BSM cells." (PMID 31969885, 2019). "Despite this, cytochalasin did not reduce MDM supernatant TNF, IL-6, and IL-1β (not shown) responses to infection with either the TIGR4 or the TIGR4 Δcps strain, with most responses actually showing non-statistically significant increases." (PMID 31551336, 2019). "The noncurliated UPEC strain showed a decrease in TNF, while after IN immunization followed by infection with this strain, TNF was absent in the kidney, indicating synergistic activation between curli and other fimbriae (type 1 and P fimbriae)." (PMID 31551993, 2019). "Upon clearance, the release of pro-inflammatory cytokines, such as IL-6, IL-8, and TNF-α, will decrease, reducing Mφ trafficking to the site of infection without altering PMN migration." (PMID 31412039, 2019). "In contrast, no patients in the TNF-i without CS group developed infection requiring discontinuation of TNF-i." (PMID 31228955, 2019). "We also explore whether a macrophage cell line can express lymphocyte markers under infection with BCG and confirmed that at the protein and mRNA levels, CD3 subunits and TNF were upregulated in a time dependent manner." (PMID 30923339, 2019). "As cyclooxygenase inhibition did not alter either inflammation or infection driven tnfa it suggests that these complex damage/infection driven mechanisms of Tnfa induction are not dependent on the HIF/COX/TNF pathway." (PMID 31611882, 2019). "In accordance with the role of NF-κB in the promotion of TNF-α expression and its role in TNF-α mediated actions, significantly higher percentage of NF-κB+ hepatocytes was found in the group of Gal-3 KO mice in comparison to WT mice, 72 h after infection." (PMID 30800112, 2019). "FIPV induced TNF-α production in infected cells; as TNF-α can itself upregulate the type II FCoV receptor aminopeptidase N, cells may thus enhance their own infection rate." (PMID 31835559, 2019). "Blood TNF-α and IL-1β levels did not change during the course of infection, which suggests that systemic inflammation does not explain the neuroinflammatory events observed in the spinal cord." (PMID 31138231, 2019).
infection (continued). "In contrast with inflammatory cytokines TGF-β, MIP-1α, and TNF-α, IL-15 is elevated in animals resistant to SIV-PAH (P = 0.01) and is inversely correlated with increased pulmonary pressures at 6 months post-infection (left panel, P = 0.0097)." (PMID 31882598, 2019). "Early after infection, TNFα, IL6 and IL12p40, but not IL1β, remained present at significantly higher levels in BAL cell supernatants from cynomolgus macaques." (PMID 31736945, 2019). "A significantly reduced expression in the bone marrow of IFN-γ, TNF-α and IFN-β, early in infection with virulent clinical Mtb strains, might contribute to this poor responsiveness of myeloid cells recruited in the lungs." (PMID 31882653, 2019). "This meta-analysis demonstrates that anti-TNF-alpha therapy slightly but not significantly increases the incidence of infection compared to other therapies in JIA children (GRADE, moderate evidence)." (PMID 30658717, 2019). "In V. vulnificus-infected fish, Epinecidin-1 could also regulate immune response genes such as IL-10, IL-1b, TNF-α, and IFN-γ and help to control the infection by enhancing the immunity." (PMID 31138331, 2019). "The results showed that the mRNA expression of IL-12 and TNF-α in the spleens and placentae were highly transcribed, but expression of TGF-β1 mRNA was dramatically dampened in the animals of RHΔrop16-inoculated mice, when compared to the RH WT infection group." (PMID 32082272, 2019). "For anti-TNF-α antibodies, infections can develop, up to 20% of subjects do not initially respond to therapy, and immunogenicity can occur that leads to a lack of response in up to 46% of patients over 12 months of treatment." (PMID 31867326, 2019). "In contrast, the expression levels of TNF-α (P = 0.039), IL-22 (P = 0.033) and IL-6 (P = 0.016) in jejunal mucosa at 12 h and IL-22 (P = 0.030) expression in ileal mucosa at 72 h post infection, were markedly upregulated in nonspecific yolk powder group." (PMID 31286936, 2019). "The meta-analysis confirmed that anti-TNF therapy slightly but not significantly increases the incidence of overall infection compared to non-biological therapies." (PMID 30658717, 2019). "Similar to the induction of cell death by TNFα/CHX, although the effects are slightly more modest, apoptosis produced in A549 cells after 16 h of etoposide treatment was significantly reduced in the case where ZIKV was added 2 h post-infection." (PMID 31671831, 2019). "However, 8 weeks after infection, SV/129 mice displayed a significant increase in the percentage of splenic CD4+ T cells with the capacity to secrete IFN-γ or TNF-α (at least p ≤ 0.05)." (PMID 30881923, 2019). "Upon PM2.5 exposure, the expression of TNF-α in response to M.tb MOI 1 and 5 infection or stimulation with PPD, PHA and LPS was significantly decreased in CD3+ and CD14+ PBMC compared to CD3+ and CD14+ PBMC infected with M.tb, or stimulated with PPD, PHA or LPS alone (p < 0.05)." (PMID 31731429, 2019). "These pathways, such as leukocyte transendothelial migration, MAPK signaling, TNF signaling, cell adhesion molecules, focal adhesion, and ECM-receptor interaction, were likely involved in the development of host resistance to a primary infection in TSF." (PMID 30678719, 2019). "Although GM-CSF and IL-2 were expressed in higher concentrations at 6 h post-infection in ESRD group, the production of a large number of pro- and anti-inflammatory cytokines as well as chemokines, including IL-8, IL-12p40, TNF-α, MCP-1, MIP-1b, and IL-10 was markedly decreased." (PMID 31875015, 2019). "IL-1β, TNFα, IL-6 and IFNγ were not significantly elevated during relapses compared to pre-infection values, and Monokine Induced by Interferon Gamma (MIG) was the only cytokine significantly increased during relapses." (PMID 31536608, 2019). "TNF-α, IL-1β, MPO activity, and epidermal/dermal thickness increased in the infected paw, which confirmed the peripheral inflammation at the primary foci of this infection." (PMID 31138231, 2019).
infection (continued). "TNF-α (A) and IL-1β (B) plasmatic levels were determined in control non-infected and infected mice after the infection (5–40 days) by ELISA." (PMID 31138231, 2019). "TLR8 inhibition also strongly reduced TNF and IL-6 induction by GBS and S. aureus, and reduced IL-10 production at the late time point, while TLR8-inhibition increased the level of IL-8 after 22 h of infection with the highest dose of bacteria." (PMID 31214180, 2019). "Moreover, in accordance with data about the prevalence of a polyfunctional T-cell profile in natural infection, we observed B. anthracis CD4+ T-cells able to produce both IFNγ and TNFα." (PMID 31213220, 2019). "In the current study, we showed trends toward increased baseline production of inflammatory cytokines TNF-α and CCL5/RANTES, hinting that chronic airway inflammation could contribute to defective antiviral responses upon infection observed in some patients." (PMID 31513433, 2019). "Although the H5N1 NP inhibited TNF-mediated NF-κB activation and the H5N1 NA activated NF-κB downstream of IL-1β in this paper, it has been reported that the overall NF-κB activation status upon infection by the H5N1 subtype is activated." (PMID 31772934, 2019). "Besides, serum levels for MCP-1, TNF-α, and IL-6 were increased already 3 h pi with S. aureus compared to PBS-treated mice followed by IL-12 and IFN-γ 6 h pi, indicating an infection-induced proinflammatory response." (PMID 31134074, 2019). "We confirm increased production of Th1 cytokines IFNγ, TNF, IL-12, IL-23, and IL-1β in the proximal ileum in B6 mice upon infection, while absence of IL-33R/ST2 attenuated the Th1 cytokine response." (PMID 31057534, 2019). "Pro-inflammatory cytokines (IL-6, TNF-α, IL-12, IFN-γ, and the chemokine CCL2/MCP-1) were up-regulated in plasma of morphine-treated mice collected 8 h after infection, which was interpreted to be the result of the increased systemic bacterial burdens with the pathogen in animals given morphine." (PMID 31921165, 2019). "IL-6, IL-8, TNF-α are proinflammatory cytokines, indicating that the LDNs secreted higher proinflammatory cytokines than NDNs upon SFTSV infection, and these might be one of the sources of proinflammatory cytokines in SFTS." (PMID 30717709, 2019). "From our study, GM-CSF and modulating cytokines TNF-α and IL-10 were suppressed in mice administered alcohol 0.5 or 3 h prior to infection, compared to mice not administered alcohol." (PMID 31821337, 2019). "The pro-inflammatory cytokines, including IL-1, IL-6, IL-8, and TNF-α, have been demonstrated to play an important role in delivery, which is independent of the presence of infection." (PMID 31113485, 2019). "SBCMV infection of this IBRB Tricell mixture for 96 h resulted in increased levels of IL-6, MMP9, and stem cell factor with a concomitant decrease in granulocyte-macrophage colony-stimulating factor and TNF-α." (PMID 30909422, 2019). "Infection with WT or ΔcadF but not ΔflaA/B resulted in elevated numbers of T lymphocytes in either organ (p < 0.001), and in slightly increased TNF-α secretion in the kidneys (p < 0.01–0.001)." (PMID 31131028, 2019). "NK cells stimulated by IL-12 or IL-18, secreted from dendritic cells and macrophages, produce several cytokines, principally IFN-γ, IL-1β, IL-8, IL-17A, and tumor necrosis factor alpha (TNF-α), which are involved in lung inflammatory processes and infection resistance." (PMID 31269777, 2019). "Infection with Ad-circ-Sirt1 did not affect IκBα phosphorylation or degradation following TNF-α stimulation compared to the Ad-Vector-infected control group." (PMID 30820544, 2019). "Many of these proinflammatory mediators, including IL-6, MCP-1, TNFα, IFNγ, RANTES and IL-1β, were also present at high concentrations on days 4 and 6 of infection in the spleen, a major target tissue for SFTSV replication and pathology, as well as other tissues." (PMID 31546590, 2019).